IGF1R (insulin like growth factor 1 receptor)
Diseases named in the same sentence as IGF1R in open-access papers (continued):
Sharing a sentence is not in itself a finding about the gene and the disease.
tumor (continued). "Our findings demonstrated that Klotho was a tumor suppressor and modulator of IGF-1R signaling in DLBCL, indicating that targeting Klotho may provide novel therapeutic strategy in DLBCL." (PMID 28153033, 2017). "We were not able to identify any association between IGF1R or SphK1 and tumor grade; however, p-IGF1R was inversely correlated to tumor grade in our analysis (p = 0.004)." (PMID 29207959, 2017). "Overall, these data suggest that the decreased mammary gland tumor latency time caused by chronic IGF1R activation is related to modulation of tumor progression rather than increased tumor initiation." (PMID 28173837, 2017). "For the mechanism, we found Med19 could regulate the expression of multiple genes relevant to tumor growth and metastasis, including P27, pAKT, pPI3K, IGF1R, E-Cadherin, N-Cadherin, Vimentin, ZEB2, Snail-1 and Snail-2." (PMID 28125713, 2017). "IGF1R is crucial for tumor transformation and survival of malignant cells." (PMID 28521298, 2017). "This indicates that IGF1R could be involved in transformation and tumor cell proliferation in Type IV with IGF1R amplification." (PMID 27891760, 2017). "Furthermore, we found that simultaneous over-expression of both miR-497 and miR-99a exhibited much stronger inhibitory effects on tumor growth than their individual effect, which is still correlated with significantly stronger repression of IGF1R and mTOR." (PMID 28624790, 2017). "They demonstrated that C6 tumor cells expressing an antisense IGF-1R RNA implanted for 24 hours in the subcutaneous tissue of rats evoked an anti-tumor response in the brain leading to complete brain tumor regression and long-term survival of the rats (abscopal effect)." (PMID 29113409, 2017). "Apparently the synergistic inhibition of miR-497 and miR-99a on tumor growth could be interpreted by their synergistical inhibition on expression of IGF1R and mTOR." (PMID 28624790, 2017). "However, IGF2 also binds to tumor cell surface IGF1R and IR, with preference for IR isoform A (IR-A)." (PMID 29099049, 2017). "In contrast, the anti-IGF-1R treatment seems to decrease the proliferation rate of Dunning R3327-G cells irrespectively of growth site, but likewise castration to induce apoptosis only in tumor cells growing outside the bone marrow cavity." (PMID 28447314, 2017). "Interestingly we further detected an inverse correlation of IGF1R to age (i.e. average age of menopausal status) and p-IGF1R to tumor grade and HER2 status." (PMID 29207959, 2017). "However, clinical trials with anti‐IGF‐1R therapy have yielded disappointing results due to toxicity or poor tumor response." (PMID 28112398, 2017). "A cocktail of PEG engagers with specificity to different tumour-associated antigens (for example, insulin-like growth factor 1 receptor, HER2, HER3, HER4 and c-Met) might offer a flexible yet effective treatment option for heterogeneous tumours." (PMID 28593948, 2017). "Our date suggested that the Me19 could promote PCa tumor growth by regulating pAKT, pPI3K, P27, and IGF1R expression level." (PMID 28125713, 2017). "In various tumor entities, both the overexpression of receptors and tyrosine kinases such as EGFR, HER2/neu and IGF-1R, the inhibition of tumor cell growth by kinase inhibitors and synergistic effects of combining these inhibitors with conventional chemotherapy were shown." (PMID 28591197, 2017). "If we include driver mutations downstream of IGF1R affecting the PI3K or Ras/Raf/mitogen-activated protein kinase signalling pathway, perturbed IGF1R signalling may be a driving force in up to 27% of tumours in our series." (PMID 28643781, 2017). "Since mice were chronically exposed to insulin analogues that activate (to a lesser or greater extent) the IGF1R, we postulated that the decreased tumor latency time (after X10/IGF1 stimulation) would be a direct result of an upregulated IGF1R signaling pathway." (PMID 28173837, 2017).
tumor (continued). "It has to be kept in mind that Saos-2/B10 cells are particularly sensitive to IR/IGF1R agonists; other tumour cell types could be less sensitive." (PMID 28316059, 2017). "Using immunohistochemical investigation, we previously reported that PDAC patients with IGF1R overexpression had poor survival rates, suggesting that IGF1R signaling might be correlated with tumor aggressiveness in this cancer." (PMID 27487118, 2016). "We propose that tumor cells in CSF express IGF1R, but IGFBP3 prevents IGF1 from being bioavailable." (PMID 27255663, 2016). "Furthermore, immunohistochemical analyses and PLA also using TNBC tissue samples (n = 174) demonstrate a direct interaction of uPAR with uPA and with IGF1R emphasizing additive effects of those interactions on TNBC tumour progression." (PMID 27502396, 2016). "When we set a cutoff of a FDR of 0.05, we found a significant enrichment of genes upregulated in the basal population during lactation and downregulated in the insulin-like growth factor 1 receptor (Igf1r) overexpression mouse model relative to the other tumor models." (PMID 27808166, 2016). "In a mixture of A549, H596, H322M and H441 lung tumor cells with different expression levels of HER1, HER3, IGF1R and cMet similar to the heterogenous cell populations in tumors, TsAb2v2 and TsAb3v1 induced a significantly improved tumor growth inhibition in comparison with the corresponding BsAbs." (PMID 27578890, 2016). "IGF1/IGF1R signaling was not able to enhance metastasis directly but via inducing tumor‐associated lymphangiogenesis contributing to cancer lymphatic metastasis 32 or via tumor‐associated leukemoid reaction resulting in immunosuppression." (PMID 26923183, 2016). "Moreover, we demonstrate that IGF1R play a significant role in maintaining cancer stem/progenitor-like phenotype of cancer cells, and these results in rapid tumor growth." (PMID 27179633, 2016). "We hypothesized that selective interference with IRES function would be detrimental to tumor cells which depend on IRES-mediated translation of key oncogenic proteins such as IGF1R and Myc for their survival." (PMID 27460074, 2016). "Recently, a clinical study demonstrated a correlation between IGF-1R signaling and tumor aggressiveness in PDAC patients, and increased exposure to ganitumab was found to be associated with improved overall survival and progression free survival in metastatic PDAC." (PMID 27127884, 2016). "The expression of the IGF1R gene is determined, to a large extent, at the transcriptional level, and the IGF1R promoter has been identified as a molecular target to a family of stimulatory transcription factors as well as nuclear proteins with tumor suppressor activity." (PMID 27446805, 2016). "Furthermore, the intratumoral administration of lentivirus-IGF-1R siRNA led to significant tumor growth inhibition in an established Huh7 xenograft model." (PMID 27813495, 2016). "Interestingly, crizotinib treatment in LS141 xenografts showed greater tumor growth than vehicle control perhaps as a result of activation of other RTKs such as increased phospho-c-Kit and phospho-IGF1-R signal seen on western immunoblotting." (PMID 26675259, 2016). "Several reports showed the involvement of stimulation of IR by insulin or IGF-2 in cancer cell progression suggesting that IGF-1R and IR both are therapeutic targets and inhibition of both receptors may be required for optimal tumor growth inhibition." (PMID 27127884, 2016). "IGF-1R expression in the tumor changed during chemotherapy and absent or diminished expression of IGF-1R after treatment was associated with a better pathological response." (PMID 26738606, 2016). "IGF-1R plays important roles in cell proliferation, apoptosis, angiogenesis, and tumor invasion." (PMID 26919100, 2016).
tumor (continued). "The tumour suppressive role of IGF-1R has been widely recognized in cancer cells, in stem cells." (PMID 26893485, 2016). "However, a reduction of tumor growth was observed in mice treated with a specific inhibitor for IGF1R." (PMID 27213811, 2016). "Changes of IGF-1R expression of the tumor during chemotherapy have been described previously." (PMID 26738606, 2016). "Impeding the complexes of uPAR with uPA or IGF1R may also strongly inhibit tumour progression in vivo by treating TNBC patients with inhibitors targeting these biomarkers in combination." (PMID 27502396, 2016). "Also IGF-R levels were seen to be elevated among OS patients tumor samples and further the elevated expression of IGF-1R and IGF-1 ligand correlated with the poor prognosis and survival rate in OS patients." (PMID 27058531, 2016). "Due to tumor heterogeneity, some cells in a tumor may express IGF1R, whereas other cells may express EGFR, and yet other cells may express insulin receptors, and all these cells may generate PI3K-AKT pro-survival signals." (PMID 27460078, 2016). "In addition, a recent study demonstrated a correlation between IGF-1R signaling and tumor aggressiveness in PDAC patients." (PMID 27127884, 2016). "However, when screened in conjunction with heterotypic stromal cells, our study additionally identified SHH, AKT, and IGF1R/AXL inhibitors as KRASG12D-dependent targets in tumor cells." (PMID 27087446, 2016). "The discovery that anti-CD99 0662mAb exerts its anti-tumor action by enhancing IGF-1R/RAS/Rac1 activity may seem paradoxical." (PMID 27835596, 2016). "While tumor suppressors might differ in their organ-specific expression, mechanisms of activation, type of tumors involved, and other parameters, they share the IGF1R pathway as a shared response path." (PMID 27446805, 2016). "Thus, these compounds hold potential as novel therapeutic agents targeting IGF-1R signaling for anti-tumor treatment." (PMID 27384680, 2016). "Moreover, the mutation frequency in the corresponding normal sample was comparable to that in the tumor sample and patient P83 was affected by a germline mutation in the TK-domain of ERBB3 but a somatic mutation in the ligand-binding domain of IGF1R." (PMID 27246973, 2016). "In this study, we determined whether the cell surface expression of CD24 may serve as a valuable biomarker for tumor sensitivity to anti-IGF1R therapy." (PMID 27179633, 2016). "Previous research has shown that low IGF-1R expression in the tumor is predictive for pathological complete response (pCR) in ER-positive tumors and that upregulation of IGF-1R during chemotherapy predicts a poor outcome in a relative small, heterogeneous group of BC patients." (PMID 26738606, 2016). "Moreover, the intratumoral administration of lentivirus-IGF-1R siRNA led to significant tumor growth inhibition in an established Huh7 xenograft model." (PMID 27813495, 2016). "Thus, INSR functionally enhances multistage tumor progression and conveys intrinsic resistance to IGF1R targeted therapyin pancreatic islet tumor growth." (PMID 27861515, 2016). "Cixutumumab, also known as IMC-A12, is a potent, highly selective, fully human IgG1 monoclonal blocking antibody with dual, subnanomolar inhibitory activity (IC50 = 0.6–1 nM) against IGF-1R homodimers as well as heterodimeric insulin receptor /IGF-1R in tumor cells." (PMID 26369833, 2015). "Based on its strong expression in a wide range of human cancers and the important contribution of IGF1-R dependent effects on tumor biology different IGF-1-R targeting approaches have been developed with some promising results in preclinical and early clinical trials." (PMID 26497207, 2015).
tumor (continued). "They hypothesized that engaging the IGF-1/IGF-1R system enabled tumor cells to escape anti-EGFR-mediated treatment as a consequence of IGF-1-driven stimulation of the PI3K–Akt pathway." (PMID 26528439, 2015). "And importantly, lessons learnt from targeted therapeutics across the tumor biology arena, teach us the pitfalls of mono-targeting and so it is very likely IGF-1R targeted therapeutic success lies in a multiple targeted approach and overall system destabilization, or multi-modality treatment." (PMID 25964779, 2015). "IGF/IGF-1R signaling contributes to the growth and survival of tumor cells." (PMID 26035416, 2015). "Clinical trials are warranted to assess whether therapeutic strategies targeting STAT3 or IGF-2 would circumvent tumour angiogenesis and pro-invasive consequences, overcoming innate resistance to anti-IGF-1R monoclonal antibody-based therapies." (PMID 26465273, 2015). "Unfortunately, hyperglycemia is reported to be one of the most highly occurred adverse events in clinical trials of anti-IGF-1R mAb therapy, which might benefit tumor cell growth and lower the efficacy the drug." (PMID 26287334, 2015). "Due to possible heterogeneous IGF-1R expression within the tumor, sampling errors may have occurred." (PMID 25680198, 2015). "IGF-1R positivity reflects a well-differentiated tumor with low metastatic tendency." (PMID 26251693, 2015). "Insulin receptor expression may lead to a compensatory mechanism for tumor treated with IGF-1R targets agents." (PMID 26217584, 2015). "This needs further investigation and our different mouse MG tumor banks that show different expression levels of IGF1R and IR could contribute to this." (PMID 25848982, 2015). "In this report, INSRs mediated NSCLC proliferation when only IGF-1R was blocked, suggesting that the resistant mechanisms to IGF-1R inhibitory agents may be the ability of tumor cell to switch from IGF-2/IGF-1R to IGF-2/INSR-A dependency." (PMID 26217584, 2015). "We analyzed the effects of the combined inhibition of IGF-1R and Src on tumor growth in vivo." (PMID 26041671, 2015). "Similarly, studies have demonstrated that IGF1R and mammalian target of rapamycin (mTOR), components of IGF1R signaling pathway, are target genes of another tumor suppressor miRNA, the miR-99a." (PMID 26504785, 2015). "Moreover, IGF-1 promotes proliferation and survival of TNBC cells, and is involved in tumor metastasis and invasion, increasing the appeal of targeting the IGF-1R pathway." (PMID 26510816, 2015). "However, recent failure of clinical trials for IGF-1R inhibitors reveals the need for a better understanding of how this pathway functions in specific tumor subtypes." (PMID 26106366, 2015). "In patients with NSCLC, the greatest activation of IGF-1R was observed in tumours that expressed high levels of IGFBP-3, although it is not clear whether this activation was ligand dependent." (PMID 25866791, 2015). "Further insights into this complex crosstalk, may help us overcome some disappointing clinical results and allow the translation of novel molecules and strategies to specifically suppress the IGF-1R-induced tumor promoting effects." (PMID 25743390, 2015). "The limited effectiveness of anti-IGF1R antibodies has been attributed to tumor resistance." (PMID 25699021, 2015).
tumor (continued). "Taken together, these data support the hypothesis that dysregulation of Notch signaling with down-regulation of IGF-1R signaling leads to accelerated tumor development in the presence of active Wnt signaling." (PMID 26106366, 2015). "In contrast, miR-675, the miRNA derived from H19, exhibits antagonistic behavior and functions as a tumor suppressor by repressing the IGF1R (Insulin like Growth Factor 1 Receptor) expression, thus the levels of these two transcripts help in maintaining cellular homeostasis." (PMID 26082843, 2015). "In both these reports, inhibition or genetic manipulation of DVL3 or RAD51 increased the sensitivity of tumor cells to IGF-1R inhibition, representing a subset of patients who might benefit from IGF-1R inhibition." (PMID 26217584, 2015). "Thus, IGF-1R blockade can inhibit tumor growth, angiogenesis and enhance chemotherapy-induced apoptosis." (PMID 26307972, 2015). "Indeed, an overexpression of IR/IGF-1R has been detected in breast malignancy, and a high expression of these receptors was shown to be tumorigenic in mouse tumor models." (PMID 25798130, 2015). "By identifying in which tumor types the IGF1R pathway actively drives tumor initiation and progression, we can better define the subtype(s) that may benefit from anti-IGF1R therapies." (PMID 25964777, 2015). "Therefore, resistance to anti-IGF-1R therapy is not only likely to be due to activities in the tumour cells but also due to the complex interplay between tumour cells and their neighbouring heterologous stromal cells within the TME." (PMID 26465273, 2015). "Furthermore, the addition of IGF-1 to the PLC/PRF/5 cell line induced increased cell proliferation in a dose dependent manner, showing that the major tumor promoting effects of IGF ligands on HCC are exerted through IGF-1R." (PMID 26329608, 2015). "Similar, crizotinib can be administered to patients with ROS1-rearranged NSCLC that do not express ALK or c-Met, as LDK378 (Ceritinib) and AP26113 ALK inhibitors demonstrate clinical efficacy on crizotinib-resistant NSCLC tumours with increased abundance of IGF-1R and ROS proteins." (PMID 26147305, 2015). "However, membrane IGF1R positivity also correlated with lower tumor grade in a recent study, which would be indicative of a favorable prognosis." (PMID 24392142, 2014). "The results were compared with the response to IGF1R antibody in xenograft tumor models." (PMID 25170759, 2014). "Also, the inverse relationship between expression of let-7b and IGF-1R/IRS-2 was confirmed in OSCC tumor xenografts and clinical specimens." (PMID 24810113, 2014). "Indeed, overexpression of IGF-1R was found to induce the growth of tumor cells and to protect cells from apoptosis under a wide variety of proapoptotic inducers." (PMID 24961901, 2014). "Taken together, our results not only reveal a critical role for miR-143 and miR-145 as tumor suppressors in colorectal carcinogenesis through repression of IGF1R translation but also show that different miRNAs within a cluster can simultaneously repress a given target mRNA." (PMID 25474488, 2014). "Understanding the molecular aberrations which result in increased tumor response to anti-IGF1R therapy could allow for the selection of patients most likely to benefit from IGF1R targeted therapy." (PMID 25170759, 2014). "IGF1R activation constitutes a cardinal step in tumor progression." (PMID 24904527, 2014). "In HCC tumor samples, IGF-1R expression was low in 24 of 27 patients." (PMID 25052889, 2014). "However, compared to PPP treatment with anti-IGF-1R antibodies exhibited relatively weak anti-tumor effects in preclinical models, and have yielded disappointing clinical data." (PMID 25268741, 2014).